IL1B (interleukin 1 beta)
Diseases named in the same sentence as IL1B in open-access papers (continued):
Sharing a sentence is not in itself a finding about the gene and the disease.
Sepsis (continued). "In addition, the secretion of IL-6 and IL-1β by PGN-stimulated DCs may contribute to sepsis pathology when bacteria and PGN reach high levels in the blood or tissues." (PMID 36677464, 2023). "In addition, the DC production of pro-inflammatory IL-6 and IL-1β upon PGN stimulation could exacerbate the inflammatory sepsis pathology in instances when the bacteria and PGN reach high levels in the blood or tissues." (PMID 36677464, 2023). "In addition, IL-1β also has an important role in the pathologic course of sepsis." (PMID 37381714, 2023). "MIF is a crucial factor in the development of sepsis, being involved in the recruitment of inflammatory cells such as macrophages, basophils, neutrophils, and eosinophils to the site of inflammation, resulting in an extensive release of different proinflammatory cytokines such as IL-1β and TNF-α." (PMID 38313162, 2023). "Besides, several published studies have reported that cytokines such as IL-1β may act as cardiodepressant inflammatory mediators during sepsis." (PMID 35399644, 2022). "These compounds exhibit protective effect on cardiac, lung, liver, and kidney against sepsis-induced acute organ damage, and several studies showed the ability of these phytochemicals to modulate cytokines related to inflammation such as IL-6, IL-1β, and TNF-α." (PMID 36588685, 2022). "Likewise, NLRP3/IL-1β inflammasome pathway inhibition attenuates cardiac atrophy in sepsis." (PMID 36359339, 2022). "Among the cytokines identified, IL-1β had the highest AUC value (0.78; p <0.001) in differentiating children with sepsis from clinical malaria, whereas IL-7 showed a greater potential in distinguishing patients with sepsis from febrile controls (AUC of 0.92, p<0.0001)." (PMID 35811678, 2022). "We previously found that miRNA treatment of MSCs can affect their proliferation and function; IL-1β pretreatment can enhance the migration ability and immunosuppressive effect of MSCs, and exosomal miR-146a contributes to the enhanced therapeutic efficacy of IL-1β-primed MSCs against sepsis." (PMID 36591221, 2022). "Additionally, repression of the NLRP3/IL-1β axis may exert protection against endothelial relaxation dysfunction induced by sepsis." (PMID 35508474, 2022). "In addition, sepsis-associated systemic inflammation was alleviated by the treatment of HO-1 inducers and CORM-2, as indicated by a drop of proinflammatory cytokines, including TNF-α, IL-1β and interferon-β." (PMID 35409029, 2022). "TNF-α, IL-1β, and IL-6 are the major inflammatory factors that could contribute to sepsis." (PMID 36142743, 2022). "MiR-451a was positively associated with TNF-α (rs = 0.206, p = 0.026), IL-1β (rs = 0.209, p = 0.023), CRP (rs = 0.328, p < 0.001), and the APACHE II score (rs = 0.272, p = 0.003), while it did not relate to IL-6 (rs = 0.141, p = 0.129) in the patients with sepsis." (PMID 35992658, 2022). "However, how IL-1β mediates neonatal sepsis-induced cognitive impairment, particularly during the developing period of the CNS, remains unclear." (PMID 35883093, 2022). "Nevertheless, it could be interesting to characterize the role of brite adipocytes in case of local or more sustained infections as sepsis, as they released high quantity of IL-1RA in response to bacteria exposition, a cytokine known to counteract IL-1β dependant inflammation." (PMID 34437647, 2021). "Because we have previously shown that IL‐1β mediates skeletal muscle atrophy in vivo and myocyte atrophy in vitro, we hypothesized that this pro‐inflammatory cytokine also targets cardiomyocytes and the heart during sepsis." (PMID 34472725, 2021). "Moreover, a short-term CLP model of sepsis upregulated IL-1β mRNA." (PMID 33825987, 2021). "Our results showed a close association between TNF-α production but not IL-1β or IL-6 with the NLRP3 29940 G>C variation in sepsis patients, which might be due to the complex inflammatory system in the host." (PMID 34172780, 2021).
Sepsis (continued). "Conversely, patients with IFN-γ<83 pg/ml and IL1β<8 pg/ml may complicated with sepsis." (PMID 33717147, 2021). "Reduced regional blood flow in the brain in rats exposed to LPS, to model septicaemia that resulted in microglial activation and neuronal loss, was associated with enhanced transcription of several cytokines and chemokines including TNF-α, IL-1β, TGF-β and MCP-1 within the brain." (PMID 33723589, 2021). "Pyroptotic cells release IL-1β and IL-18 and then stimulate and recruit neutrophils and macrophages to the focus of infection, which may be an effect of pyroptosis in the early stage of sepsis." (PMID 34257519, 2021). "In addition, IL-17 enhances the proinflammatory responses induced by IL-1β, implying that astaxanthin might downregulate the production of IL-1β and IL-17 to protect LPS-induced sepsis." (PMID 34677433, 2021). "Recent evidence demonstrates that NLRP3/IL-1β activation is associated with the severity of SAE and that inhibiting the adverse effects of NLRP3 inflammasomes may be a good strategy to avoid excessive inflammation during sepsis." (PMID 34062710, 2021). "Interestingly, cytokine network analyses have revealed a network formed by IL‐1β, IL‐6, and IL‐10 during the first day of sepsis, suggesting that these cytokines may take a crucial role in the acute phase of sepsis." (PMID 33719215, 2021). "In the acute phase of sepsis, macrophages polarize into the M1 phenotype to activate TLRs or other recognition receptors due to impaired intestinal barrier function, bacterial translocation, and increased inflammation, releasing a variety of inflammatory cytokines, such as IL-1β, IL-6, and TNF-α." (PMID 35003009, 2021). "Moreover, the ROC curve illustrated that CRP (AUC [95%CI]: 0.755 [0.636–0.874]), TNF‐α (AUC [95% CI]: 0.660 [0.534–0.786]), IL‐1β (AUC [95% CI]: 0.665 [0.549–0.781]), and IL‐6 (AUC [95% CI]: 0.622 [0.507–0.737]) all had potential in discriminating sepsis deaths from sepsis survivors." (PMID 34761437, 2021). "In addition, we showed that treatment with CE reduced plasma IL-1β in an LPS-induced sepsis model." (PMID 34692754, 2021). "Overall, we show that IL‐1β is involved in the pathogenesis of systolic and diastolic dysfunction by decreasing cardiomyocyte contractility and relaxation and that inhibition of IL‐1β could have beneficial effects in sepsis." (PMID 34472725, 2021). "IL-1β released by the mtROS/NLRP3 inflammasome pathway in platelets has been correlated with increased vascular permeability, which may cause irreversible shock during sepsis." (PMID 33324236, 2020). "The in situ decrease (or lack of expression) in Th1 pro-inflammatory cytokines (IL-6, IFN-y, IL-1β, IL-2r, and IL-12) and the increase in IL-10 indicate that there is an inhibition of the innate and acquired immunity during the acute and severe phases of leptospirosis and sepsis." (PMID 31114579, 2019). "Furthermore, lipid-lowering therapies hold a very competitive risk/benefit balance even when very low LDL levels are reached, while this is not the case for IL-1β blockade, which is associated with a higher risk of sepsis and fatal infections." (PMID 31652822, 2019). "First, we did not establish whether EV miRNA-466 family molecules aggravate lung injury of mouse ARDS model in this study, whereas our data is consistent with previous study demonstrating that GW4869, an inhibitor of EV release, decreased serum levels of IL-1β in a sepsis-induced inflammation." (PMID 31221118, 2019). "In murine CLP-sepsis, human adipose-derived mesenchymal stem cells were able to modulate sepsis by downregulation of Th1-cell responses, associated with lower levels of pro-inflammatory cytokines (TNF, IL-1β, IL-6, IL-12, IFNγ) and higher levels of anti-inflammatory IL-10 derived from macrophages." (PMID 31114571, 2019).
Sepsis (continued). "However, IL-1β can also contribute to substantial tissue damage, an overabundance of inflammatory cell recruitment, and uncontrolled cytokine signaling in severe cases, such as during E. coli-induced sepsis and P. aeruginosa-induced pneumonia." (PMID 30018884, 2018). "Furthermore, NET inhibitor Cl-Ad suppressed the release of TNF-α and IL-1β in PLF after sepsis." (PMID 29789550, 2018). "During sepsis, systemic activation of the innate immune system by PAMPs and DAMPs results in severe and persistent inflammatory responses characterized by an excessive release of inflammatory cytokines such as IL-1β, TNF, and IL-17, collectively known as the “cytokine storm”." (PMID 29163354, 2017). "Sepsis in general can result in multiple organ failure and death as a consequence of uncontrolled activation of the innate immune system with high circulating levels of pro-inflammatory cytokines such as interleukin 6 (IL-6), IL-8, IL-1β and tumor necrosis factor α (TNFα)." (PMID 28428949, 2017). "However, the association between IL-1β expression level and prognosis in patients with sepsis has not yet been established." (PMID 25780458, 2015). "Indeed, recent evidence suggests that high-dose cholecalciferol (vitamin D3) supplementation in patients with severe sepsis or septic shock increases systemic cathelicidin levels, while modulating immunoregulatory cytokines such as interleukin (IL)-1β and IL-6." (PMID 26380991, 2015). "Furthermore, azithromycin specifically affected IL-1β levels in a murine endotoxin sepsis model." (PMID 26152605, 2015). "In this meta-analysis, two polymorphisms (IL-1B + 3594 and IL-1RN VNTR) were significantly associated with sepsis susceptibility in overall comparison and subgroup analyses based on sepsis severity, whereas IL-1A-889 polymorphism influenced sepsis risk only in overall comparison." (PMID 24428862, 2014). "The aim of the present study is to evaluate whether sepsis activates NLRP3 inflammasome/caspase-1/IL-1β pathway in cardiac fibroblasts (CFs) and whether this cytokine can subsequently impact the function of cardiomyocytes (cardiac fibroblast-myocyte cross-talk)." (PMID 25216263, 2014). "Sepsis enhances the transcription of several pro- and anti-inflammatory cytokines and chemokines in the brain, including tumor necrosis factor alpha (TNFα), interleukin-1 beta (IL1β), transforming growth factor beta (TGF β), and monocyte chemoattractant protein 1 (MCP1)." (PMID 23718252, 2013). "Furthermore, considering the CD55 expression levels on neutrophils from WT, Il-1r−/−, Il-10−/−, and Nod2−/− mice with CLP, it is conceivable that NOD2-mediated IL-10 production suppresses CD55 expression on peritoneal neutrophils during sepsis in both IL-1β-dependent and IL-1β-independent manners." (PMID 23675299, 2013). "Therefore, agents attenuating TNF-α and/or IL-1β expression may have potential as treatments for prevention of lethal sepsis." (PMID 24260470, 2013). "The pathogenesis of sepsis-induced mitochondrial injury is associated with free radical generation and the release of a variety of exacerbating inflammatory mediators (e.g. TNF-α, IL-1β and IL-6) which directly or indirectly influence mitochondrial function and energy production." (PMID 24039949, 2013). "Thus, IL-1β and IL-8 may be independent predictors of progression from severe sepsis to septic shock." (PMID 22220196, 2011). "Pro‐inflammatory IL‐1β, IL‐6, IL‐8, IL‐12/23p40, TNF‐α, and IFN‐γ, and anti‐inflammatory (regulatory) cytokine IL‐10 play key roles in the acute phase of sepsis." (PMID 41474380, 2026). "This process triggers the release of IL-6, IL-1β, and TNF-α, which drive systemic inflammation, sepsis, septic shock, and disseminated intravascular coagulation (DIC)." (PMID 41521316, 2026). "L-carvone therapy (at low, moderate, and high doses) led to markedly lower kidney IL-1β expression and TNF-α concentrations than observed after sepsis/LPS induction." (PMID 41585603, 2026).
Sepsis (continued). "All doses of carvone substantially ameliorated proinflammatory cytokine amounts (IL-1β gene expression and TNF-α levels), in contrast to the sepsis/induction model." (PMID 41585603, 2026). "Serum levels of IL-6, TNF-α, IL-1β, and HMGB1 were markedly elevated in sepsis groups compared to Sham (P < 0.001)." (PMID 41281995, 2025). "In sepsis-induced acute lung injury, upregulation of lncRNA H19 inhibited TNF-α, IL-1β, IL-6, IL-10, and BAX to suppress pulmonary apoptosis and inflammation." (PMID 39940682, 2025). "During the early phases of sepsis, pro-inflammatory cytokines such as tumor necrosis factor-alpha (TNF-α), interleukin-1β (IL-1β), and interleukin-6 (IL-6) are released, initiating the inflammatory cascade." (PMID 40566580, 2025). "This study underscores the pivotal role of necroptosis in the pathophysiology of sepsis, as reflected by elevated levels of RIPK1, IL-1β, and IL-18 and reduced expression of caspase-8 across both pediatric and adult patients." (PMID 40722817, 2025). "A previous report, using LPS administration as a sepsis model, demonstrated that CD38 promotes the expression of proinflammatory cytokines, including IL-1β, IL-6, and IL-12." (PMID 41488275, 2025). "Elevated levels of senescence-associated secretory phenotype (SASP) markers, including IL-6, IL-1β, and TNF-α, have been detected in mice subjected to cecal ligation and puncture (CLP) to induce sepsis." (PMID 40153575, 2025). "First, it provides a comprehensive analysis of multiple inflammatory markers, including CRP, IL-1β, IL-6, IL-8, IL-10, PCT, and TNF-α, which offers a detailed understanding of the immunomodulatory effects of ulinastatin in the treatment of sepsis." (PMID 40667510, 2025). "Subsequently, we measured the mRNA expression of SLC25A22, SLC25A33, and SLC25A37, along with that of pro-inflammatory cytokines, including TNF-α, IL-6, and IL-1β, in CD14+ monocytes from sepsis patients with liver abscesses." (PMID 40384854, 2025). "To characterize the anti-inflammatory effect of DTP against LPS-induced sepsis, we quantified the concentrations of the inflammatory markers TNF-α, IL-6, and IL-1β in mouse serum by ELISA." (PMID 41009021, 2025). "The findings revealed a significant elevation in the levels of interleukin-1β (IL-1β), interleukin-6 (IL-6), and tumor necrosis factor-α (TNF-α) in both BALF and serum of sepsis-induced ALI mice." (PMID 41496909, 2025). "We observed that enhancing O-GlcNAcylation of FTO using an OGA inhibitor (TMG) decreased LPS-induced TNF-α/IL-1β/IL-6 inflammation and reduced septic mouse mortality, which may constitute a protective mechanism to limit exacerbated inflammation in acute stress conditions such as LPS-induced sepsis." (PMID 40642069, 2025). "The sepsis-induced immune response produces an abundance of pro-inflammatory factors (TNF-α, IL-1β), which bind to specific receptors and activate apoptotic signaling pathways such as Fas and Caspase." (PMID 40823184, 2025). "Toll-like receptors (TLRs) are commonly activated receptors in sepsis, leading to the activation of NF-κB and the subsequent release of inflammatory factors, such as TNF-α, IL-1β, IL-6, and IL-18." (PMID 41311552, 2025). "Elevated levels of potent cytokines, including IL-6, IL-1β, and TNF-α, are detectable in patients diagnosed with early-stage sepsis." (PMID 41256846, 2025). "Sepsis-induced cholestasis, common in critical illness, is mediated by cytokines such as TNF-α, IL-1β, and IL-6, which disrupt bile transport, leading to intrahepatic cholestasis and raised conjugated bilirubin, ALP, and GGT." (PMID 40228343, 2025). "When sepsis occurs, NF-κB activation and the release of acute inflammatory cytokines including TNF-α and IL-1β inhibit FXR activity, leading to bile acid metabolism imbalance." (PMID 40430579, 2025). "XBJ exerted therapeutic effects on sepsis and septic-AKI through suppression IL-1β/MMP9, IL-6/MMP9 and TNFα/MMP9 at both mRNA and protein level." (PMID 41042728, 2025).
Sepsis (continued). "When the cutoff value for plasma IL-1β was set at 8.47 pg/mL, its AUC for predicting AKI in sepsis patients was 0.837 (95% CI: 0.754-0.921)." (PMID 40385253, 2025). "For instance, aerobic glycolysis mediated by pyruvate kinase M2 (PKM2) has been shown to promote inflammasome activation in macrophages via EIF2AK2 phosphorylation, exacerbating the release of pro-inflammatory cytokines like IL-1β and HMGB1 in sepsis." (PMID 40755920, 2025). "Compared with control mice, these mice presented decreased levels of proinflammatory cytokines, such as IL-1β, IL-6, and TNF-α; reduced sepsis-induced organ injury; and improved survival." (PMID 39675717, 2025). "Here, we found that these DEGs are primarily enriched in IL1B+ macrophages or CD14+ monocytes from IBD and sepsis patients." (PMID 39993996, 2025). "The hyperactivation of the immune system during sepsis leads to a cytokine storm, characterized by the excessive release of pro-inflammatory cytokines, including tumor necrosis factor-alpha (TNF-α), interleukin-1 beta (IL-1β), and interleukin-6 (IL-6)." (PMID 39803908, 2025). "In the sepsis cell model, miR-539-5p has also been found to regulate the levels of TNF-α and IL-1β in cardiomyocytes." (PMID 40955148, 2025). "In the context of sepsis, inflammatory factors such as tumor necrosis factor-α (TNF-α) and interleukin-1β (IL-1β) modulate HIF-1α expression by activating the NF-κB pathway." (PMID 40887582, 2025). "Statistical analysis was performed on serum concentrations of CRP, IL-6, IL-1β, TNF-α, IL-10, and PDL1 from healthy individuals and sepsis patients, using a 95% CI." (PMID 40568710, 2025). "In our model, CLP-induced sepsis increased the renal expression of NLRP3, caspase-1 in its mature and activated form, and IL-1β, consistent with previous reports." (PMID 40869248, 2025). "High-dose levosimendan significantly reduced TNF-α, IL-1β, IL-6, and MCP-1 levels by the 10th hour, accompanied by improved Murine Sepsis Scores." (PMID 40566580, 2025). "Studies in sepsis models revealed that TREM-1 knockout mice express lower levels of IL-6, TNFα, and IL-1β compared to wild-type mice after eCIRP injection." (PMID 40332009, 2025). "Treatment with MP-10 led to a lower murine sepsis score (MSS), reduced plasma IL-1β levels, alleviated thrombocytopenia, and decreased fibrin deposition in the spleen." (PMID 40429643, 2025). "The cytokine storm is a dangerous hyperinflammatory state associated with elevated levels of several pro-inflammatory cytokines (IL-1β, IL-2, IL-6, IL-17, IL-8, TNF-α) and chemokine L2 (CCL2) and it is an integral part of sepsis." (PMID 40650213, 2025). "Given that multi-organ dysfunction in sepsis is primarily driven by a hyperinflammatory cytokine storm, we examined serum levels of TNF-α, IL-6, and IL-1β and found that ILA effectively mitigated systemic inflammatory response." (PMID 40761792, 2025). "These elevated eCIRP levels, observed in the context of these inflammatory diseases, induce macrophage production of TNF-α, IL-1β, and IL-6, contributing to multi-organ dysfunction, including ALI and acute kidney injury (AKI) in sepsis." (PMID 40332009, 2025). "The innate and adaptive immune systems release inflammatory cytokines early in sepsis to eliminate foreign pathogens, such as IL-6, TNF-α, and IL-1β." (PMID 40718494, 2025). "Sepsis-induced hyperinflammation is primarily driven by TNF-α, IL-6, and IL-1β, whose plasma levels negatively correlate with survival in patients." (PMID 41157235, 2025). "In the CLP-induced sepsis kidney injury model, the IL-2 gene exhibited low expression, whereas the CXCL8, IL-1β, TNF, IL-6, and IL-10 genes demonstrated high expression levels." (PMID 40166075, 2025). "Acute lung injury (ALI), caused by both infectious and non-infectious sources such as severe trauma, hyperoxia, and sepsis, is characterized by dysregulated inflammatory responses, including massive release of cytokines (e.g., TNF-α, IL-1β, IL-6, and IL-8)." (PMID 41394141, 2025).